ABCA1 (ATP binding cassette subfamily A member 1)
Diseases named in the same sentence as ABCA1 in open-access papers (continued):
Sharing a sentence is not in itself a finding about the gene and the disease.
cancer (continued). "Our study thoroughly illustrates the impact of ABCA1’s systemic presence across various forms of cancer." (PMID 40297807, 2025). "Increased mitochondrial cholesterol is critical for cancer phenotypes, and the PI3K/AKT pathway elevates mitochondrial cholesterol levels to support cancer cell survival through the inhibition of ABCA1-mediated cholesterol efflux." (PMID 40002387, 2025). "We used the EPIC and MCPCOUNTER algorithms to study the correlation between the infiltration of CD8+ T cells and cancer-related fibroblasts and the expression of ABCA1 in different malignant tumours." (PMID 40297807, 2025). "Variants classified as pathogenic across all five tools were cross-referenced with known cancer genes, identifying high-confidence mutations in FLNC, MAP2K1, and ABCA1." (PMID 41373405, 2025). "LXR agonists synergize with sHDL nanodiscs by increasing the expression of the ABCA1 cholesterol CpG oligonucleotides are established adjuvants used in cancer immunotherapy that work through the toll-like receptor 9 pathway." (PMID 40236100, 2025). "Given its specificity to tumors, ABCA1 holds promise as a biomarker for cancer diagnosis, monitoring for recurrence, and predicting outcomes." (PMID 40297807, 2025). "On the other hand, miR-324–3p can target ATP-binding cassette transporter A1 (ABCA1), which is implicated in the efflux of drugs from cancer cells, making them resistant to chemotherapy." (PMID 39136001, 2024). "Drug transporters such as ABCA1 play a critical role in pretargeted drug resistance, which elucidates the ability of cancer cell to adapt to different drugs by increasing drug production and decreasing drug absorption." (PMID 38827789, 2024). "Cholesterol and its isoprenoid precursor IPP are endogenous substrates of ABCA1, and IPP efflux via ABCA1 is the driver of Vγ9Vδ2 T-lymphocyte-mediated immuno-killing of cancer cells." (PMID 39107857, 2024). "This implies that upregulated ABCA1 reduces cholesterol accumulation by facilitating cholesterol efflux from the cells, thereby enhancing the sensitivity of cancer cells to the antitumor drugs." (PMID 39349433, 2024). "Emerging data suggests that cancer cells secrete factors that activate cholesterol transporters in macrophages such as ABCA1 ABCA6 and ABCG1 to increase cholesterol efflux." (PMID 37872251, 2024). "Although the exact role of ABCA1 in cancer remains controversial, ABCA1 was recently identified as a potential therapeutic target in cancer." (PMID 39349433, 2024). "As the expression of insufficient quantity of ABCA1 leads to accumulation of cholesterol in cancer cells, prevent releasing of mitochondrial TNF, and hence accelerates the development of the disease." (PMID 38827789, 2024). "As the role of ABCA1 in tumorigenesis has become increasingly evident, there is increasing evidence that ABCA1 contributes to cancer development as well as malignant phenotypes and drug resistance." (PMID 36672209, 2023). "The regulation of intracellular cholesterol levels by ABCA1 has an indirect impact on the proliferation, migration, and invasion of cancer cells." (PMID 37874419, 2023). "For instance, ABCA1 is typically studied as a cancer suppressor due to its role in reducing intracellular cholesterol levels." (PMID 38062450, 2023). "Accordingly, clinical trials are underway to assess the efficacy of ABCA1-targeted treatment in malignant tumors across different cancer types." (PMID 37874419, 2023). "ABCA1, the ATP-binding cholesterol A1 transporter/exporter in human cancer cells, has been shown to reduce the amount of mitochondrial cholesterol, resulting in the release of molecules that promote cell death." (PMID 37894640, 2023). "Third, several studies indicate that the chol transporter ABCA1 is involved in several types of cancer cells but contradictory data arise." (PMID 36439249, 2022).
cancer (continued). "Although in the case of miR-199a-5p, a reciprocal regulation between hypoxia and this miRNA has been found in cancer cells, to our knowledge, this is the first report showing the relationship between miR-199a-5p and hypoxia in macrophages and ABCA1 regulation." (PMID 36407436, 2022). "Hypermethylation silences ABCA1, resulting in elevated intracellular cholesterol levels, which contributes to cancer progression." (PMID 35682652, 2022). "There are conflicting pieces of evidence demonstrating the biological roles of ABCA1 in cancer biology." (PMID 35454786, 2022). "ATP-binding cassette transporter A1 (ABCA1) protein is a cholesterol and phospholipid transporter across the cell membrane, and mutation of this gene is associated with cancer and lipoprotein metabolism abnormality." (PMID 35741817, 2022). "Since intracellular cholesterol accumulation plays a key role in cancer progression, ABCA1 has been proposed as a potential therapeutic target; nevertheless, this subject needs further investigation." (PMID 33562440, 2021). "RBP‐HuR regulates cellular cholesterol metabolism by mediating ABCA1 gene expression in cancer cells." (PMID 34047477, 2021). "Our results show that CEBPD can directly bind to the SOX2, OCT4, NANOG, and ABCA1 promoter regions to promote the properties of cancer stemness and drug resistance." (PMID 33436575, 2021). "ABCA1 knockdown in the DDP-resistant cell lines that were overexpressing miR-106a significantly decreased the cancer cells’ apoptotic rate in the presence of DDP." (PMID 34281263, 2021). "Several groups have provided insights into the molecular mechanisms of ABCA1 in cancer biology to help understand its pathophysiology and to identify potential therapeutic targets." (PMID 33562440, 2021). "Reduced activity of ATP binding cassette subfamily 1 (ABCA1) in cancer cells increases mitochondrial cholesterol levels, promoting cancer cell survival." (PMID 33113804, 2020). "SIRT1 positively regulates the expression of ABC transporters, such as MDR1 and ABCA1, which promote efflux of anti-cancer drugs from cells." (PMID 32151067, 2020). "The anticancer function of ABCA1 in human cancer cells has been demonstrated and is probably related to its ability to decrease the content of mitochondrial cholesterol resulting in the release of cell death-promoting molecules." (PMID 32982759, 2020). "Cancer cells upregulate the ATP-binding cassette transporter ABCA1 to increase cholesterol efflux, and overexpression of ABCA1 in human cancers increases metastasis." (PMID 32509584, 2020). "Another gene that controls cholesterol homeostasis is ABCA1, a cell membrane cholesterol exporter, and it is dysregulated in cancer cells." (PMID 30717356, 2019). "The high conservation of NFAT and HOXA elements can be probably attributed to the ABCA1 transport function and suggests a connection between ABCA1 protein and cancer." (PMID 31234415, 2019). "ABCA1 plays an inevitable role in the resistance against tumorgenesis through depletion of cholesterol from cells under cancer threat, where cancer onset requires elevated intracellular cholesterol levels to build new membranes." (PMID 26664612, 2015). "Consistent with our studies, ERK1 and 2 are linked to regulation of many ABC genes, including ABCG1, ABCA1, MDR1, and MRP1 in various cancer and non-cancer cells." (PMID 21159167, 2010). "This should be detrimental in theory since it increases exposure to the toxic effect of free cholesterol, but cancer cells deploy countermeasures: upregulating ABCA1 to move cholesterol out of cells and sequestering esterified cholesterol in the form of lipid droplets." (PMID 41521893, 2026).
cancer (continued). "To examine whether the enrichment of ABCA1 protein in malignant cancer cells is detectable in clinical cases, we conducted immunohistochemical analysis on surgical specimens taken from patients with primary ccRCC." (PMID 41521893, 2026). "ABCA1 is involved in the development and progression of a wide range of malignant tumors, so to further clarify the role of ABCA1 expression therein, and to search for new breakthroughs in the treatment of tumors and cancers, we launched a thorough pan-cancer analysis of ABCA1." (PMID 40297807, 2025). "Therefore, we wrote this review to explore the mechanism of action of ABCA1 in the pathogenesis and prognosis of different types of cancer, as well as its potential value in clinical diagnosis and treatment." (PMID 40297807, 2025). "From these perspectives, the expression of ABCA1 may be regulated by multiple miRNAs, leading to a role in cancer development." (PMID 40297807, 2025). "However, the ABCA1 expression is suppressed in cancer cells by the phosphatidylinositol-3-kinase (PI3K), protein kinase B (AKT), and mechanistic target of rapamycin complex 1 (mTORC1) pathway." (PMID 37835481, 2023). "Some studies have revealed that ABCA1 may affect cancer cell growth and migration by regulating the cholesterol levels." (PMID 36672209, 2023). "In addition, signalling pathways controlled by ABCA1 have emerged as essential players in controlling lipid metabolism in cancer." (PMID 37889548, 2023). "Investigation of ABCA1 impact on cancer development has been analyzed in several studies." (PMID 37312227, 2023). "Similarly, MiR-27a-3p also prevents cancer cell death by inhibiting cholesterol efflux or by targeting ABCA1." (PMID 37835481, 2023). "Epidemiological and experimental evidence suggests that ABCA1 may be involved in the progression of certain cancer types." (PMID 36672209, 2023). "Indeed, the close relationship between the EMT pathway and the unfavorable evolution of malignant tumors involving ABCA1 is evident." (PMID 37874419, 2023). "Moreover, ABCA1 expression clearly correlates with a shorter cancer-specific overall survival and shorter disease-free survival." (PMID 37312227, 2023). "Similarly, decreased ABCA1 expression triggered by hypermethylation elevates cholesterol levels, stimulating cancer cell development." (PMID 35682652, 2022). "In this study, we demonstrated that ABCA1 expression is highly regulated across cancer cell states." (PMID 35327383, 2022). "On one hand, decreased expression of ABCA1 has been observed in (i) cancer vs." (PMID 36439249, 2022). "These lipids are reported to severely impact many biological processes related to cancer by regulating plasma membrane cell fluidity and functionality, but information on this subfamily of transporters in cancer is dispersed, controversial and mostly limited to the ABCA1 member." (PMID 36149602, 2022). "However, this regulation was seen across both cancer cell phenotypes, and thus cannot account for the differences in the expression of ABCA1 in an EMT." (PMID 35327383, 2022). "Efforts to artificially increase the cholesterol-removing pre-β/discoidal HDL fraction to drive ABCA1-mediated net cholesterol depletion from cancer cells might therefore provide a molecular axis that offers therapeutic potential for the treatment of PDAC." (PMID 35577388, 2022). "In the case of ABCA1 is a protein whose inhibition promotes cancer progression." (PMID 33649335, 2021). "Therefore, metastatic cancer cells substantially reduce their cholesterol levels in the plasma membrane compartment by overexpressing ABCA1, which eventually mediates cholesterol efflux." (PMID 34109128, 2021). "Similarly, miR-27a-3p also inhibits cancer cell apoptosis by blocking cholesterol efflux or targeting ABCA1." (PMID 34303383, 2021).
cancer (continued). "IPP can also be secreted from cancer cells and APCs into the extracellular environment to activate Vγ9Vδ2 T cells, and this mechanism was shown to involve the ATP-binding cassette transporter A1 (ABCA1) in cooperation with apolipoprotein A-I (apoA-I) and BTN3A1." (PMID 34944832, 2021). "Thus, the consequences of ABCA1 down or upregulation should be thoroughly investigated in different types and stages of cancer." (PMID 33562440, 2021). "Mechanism of ABCA1 involvement in the pathophysiology of cancer is complex." (PMID 34281263, 2021). "However, in cancer cells, ABCA1 expression is inhibited via the phosphatidylinositol-3-kinase (PI3K)/protein kinase B (AKT)/mechanistic target of rapamycin complex 1 (mTORC1) pathway." (PMID 34303383, 2021). "Some of these targets could be related to changes in the biosynthesis, metabolism, and redistribution of cholesterol in cancer cells due to for example increased expression of ABCA1 and formation of LDs leading to ER stress and cell death." (PMID 32982759, 2020). "ABCA1 is believed to inhibit the proliferation and metastasis of many cancers." (PMID 32430024, 2020). "Our findings suggest that RASSF1C may promote cancer cell drug resistance through up-regulation of the ABCA1 gene expression and down-regulation of miR-33a expression." (PMID 30719208, 2019). "Lower levels of ABCA1 increase mitochondrial cholesterol levels and promote cancer cell survival." (PMID 30717356, 2019). "Several studies have mentioned that, ABCA1, a major cellular cholesterol efflux transporter, might be involved in the pathogenesis of cancer." (PMID 31598156, 2019). "ABCA1 has an anti-cancer activity dependent on lipid transport activity." (PMID 30283400, 2018). "Collectively, in addition to a well-known role in HDL biogenesis, ABCA1 acts to fine-tune membrane lipid compositions to modulate PM functionality that may alter cancer cell phenotypes in a cell type-dependent manner." (PMID 30283400, 2018). "In addition, LXR agonist or ABCA1 over-expression has been shown to alter cholesterol content in degenerating neurons or cancer cells." (PMID 26076474, 2015). "Furthermore, we also were able to identify genes such as BRCA1, ABCA1, TNFRSF1B, MLLT11 that have been associated with various types of cancers." (PMID 22594378, 2012). "Consequently, our research could significantly bolster the case for utilizing ABCA1 in the therapeutic approach to cancer." (PMID 40297807, 2025). "Interestingly, yarrow-Sep inhibited key lipid metabolic targets in CRC cells extensively shown to be implicated in cancer dissemination and prognosis —SREBF1, FASN, ABCA1 and HMGCR— and epithelial to mesenchymal targets—CDH1, ATP1B1, CDH2 and Vimentin—augmenting cell adhesion." (PMID 38576446, 2024). "FaDOH treatment showed an upregulation of ABCA1 in colon neoplastic rat tissue, suggesting a function for this transporter in the redistribution of lipids and the enhanced creation of LDs in cancer cells, which may result in endoplasmic reticulum (ER) stress and cancer cell death." (PMID 36981118, 2023). "Thus, numerous studies have investigated the role of ABCA1 in cancer development." (PMID 33562440, 2021). "There may be a dual role of ABCA1 in cancer, as several studies suggest that ABCA1 function has anticancer properties, although there is also epidemiological and experimental evidence suggesting it may be involved in progression of certain types of cancer." (PMID 33562440, 2021). "RT-qPCR showed increased expression of PPARγ2 in cancer cells and increased expression of ABCA1 in neoplastic tissue, which could indicate an increased formation of LDs in cancer cells and normal cells, thus contributing to the understanding of the anticancer and antidiabetic properties of FaDOH." (PMID 32982759, 2020). "Furthermore, the increased expression of ABCA1 could lead to further exhaustion of cholesterol from cancer cells." (PMID 32982759, 2020).
cancer (continued). "Some members of the ABC subfamily, such as ABCA1, may inhibit cancer development." (PMID 32430024, 2020). "Indeed, ABCA1 has been reported to mediate drug resistance in cancer cells." (PMID 30719208, 2019). "In this cancer type, ABCA1 seems to have an opposite effect on malignancy by unknown mechanisms." (PMID 30283400, 2018). "In addition, ABCA1 may be important for the treatment of cancer." (PMID 40297807, 2025). "These suggest that these five cholesterol-related genes (APOA1, APOC3, ABCA1, NPC2, CD36) play an important role in cancer." (PMID 40302802, 2025). "These cells recycle myelin, thus providing lipids as an energy source to cancer cells, further sustaining the mesenchymal phenotype of GBM cells via the Liver X receptor/ATP-Binding Cassette Subfamily A Member 1 (ABCA1)-dependent pathway." (PMID 39859381, 2025). "Gene-centric analyses highlight four cancer-relevant loci MAP2K1, FLNC, ABCA1, and TUBB3 as key targets of methylation deregulation, each exhibiting distinct CpG methylation patterns linked to their known biological roles in tumorigenesis." (PMID 41373405, 2025). "Tripterine also promotes cholesterol efflux mediated by ATP-binding cassette transporter A1 (ABCA1), inhibits EMT, and eventually suppresses cancer cell proliferation, migration and invasion." (PMID 38262996, 2024). "Higher expression of HIF1A, ABCA1, FPR1, CD63, and FCN1 was found in cancer compared to healthy state." (PMID 39315092, 2024). "Expression of the major ABC transporters, including ABCA1, ABCB1, ABCC1, ABCC2, ABCC3 and ABCG2, was assessed in chemoresistant cancer cells transfected with si-ERRγ." (PMID 32206097, 2020). "We demonstrate that ABCA1 is upregulated in colorectal neoplastic rat tissue, which indicates a possible role of this transporter in the redistribution of lipids and increased formation of LDs in cancer cells that may lead to endoplasmic reticulum stress and cancer cell death." (PMID 32982759, 2020). "Therefore, cancer cells proliferation may be increased followed by LXRα and ABCA1 inactivated." (PMID 29573196, 2018). "The possible involvement of cholesterol efflux via the LXR/ABCA1 pathway in growth inhibition and the potential therapeutic efficacy of novel LXR agonists should be examined in a variety of cancers." (PMID 26452260, 2015). "During the process of studying its anti-cancer properties, curcumin was found to inhibit ATP-binding cassette (ABC) family members including ABCA1, ABCB1, ABCC1, and ABCG2." (PMID 24653706, 2014). "We further demonstrated that HOXB2 modulated the expression of long non-coding RNA DANCR, a differentiation antagonizing non-protein coding RNA, and thus influenced its downstream effectors ABCA1, ABCG1, and ERK signaling to boost drug resistance and cancer proliferation." (PMID 38851728, 2024). "In contrast, LncRNA Mexis and LINC DYNLRB2-2 induce macrophage ABCA1 gene expression, which in turn promotes ABCA1-mediated cholesterol efflux leading to increased cholesterol levels in TME, which may further promote cholesterol uptake by cancer cells." (PMID 38238756, 2024). "Similarly, in our study, knocking down ALKBH5 increased the expression of ABCA1 and decreased autophagy substrate SQSTM1, which activated autophagy-related pathways for anti-cancer effects." (PMID 38481816, 2024). "ABCA1 is a transporter of cellular phospholipids and cholesterol and participates in cancer metastasis in triple‐negative breast cancer." (PMID 38385857, 2024).